WDR33 (WD repeat domain 33)
Description:
Essential for both cleavage and polyadenylation of pre-mRNA 3' ends.
Synonyms: WDC146; FLJ11294; NET14
Tractability: PROTAC: UniProt records ubiquitination sites on it; ubiquitination databases record sites on it; its protein half-life has been measured.
Gene: Protein-coding gene on chromosome 2 (127,701,027 to 127,811,187, reverse strand). Ensembl gene ENSG00000136709.
Subcellular location: Nucleus
Subcellular location (Human Protein Atlas): Nucleoli fibrillar center; Nucleoplasm
Pathways (Reactome):
Metabolism of RNA: Processing of Intronless Pre-mRNAs; Transport of Mature mRNA Derived from an Intronless Transcript; mRNA 3'-end processing; mRNA Polyadenylation
Disease: Dengue Virus-Host Interactions
Gene expression (Transcription): RNA Polymerase II Transcription Termination
Gene Ontology:
Molecular function: RNA binding
Biological process: mRNA 3'-end processing; DNA damage tolerance; spermatogenesis
Cellular component: fibrillar center; mRNA cleavage and polyadenylation specificity factor complex; nucleoplasm; nucleus
Genetic constraint (gnomAD): Loss-of-function variants: 45 observed, 157.71 expected, observed/expected ratio (o/e) 0.29, 90% interval 0.22 to 0.37. The synonymous counts are far from expectation, so gnomAD's model fits this gene poorly and the ratio says little. Missense variants: 1,091 observed, 1,730.4 expected, observed/expected ratio (o/e) 0.63, 90% interval 0.6 to 0.66. Synonymous variants: 480 observed, 581.65 expected, observed/expected ratio (o/e) 0.83, 90% interval 0.76 to 0.89.
Homologues: Orthologues: chimpanzee WDR33 (99% identical), dog WDR33 (98% identical), pig WDR33 (98% identical), rabbit WDR33 (98% identical), mouse Wdr33 (96% identical), macaque WDR33 (96% identical), guinea pig WDR33 (93% identical), rat Wdr33 (76% identical), tropical clawed frog wdr33 (68% identical), Drosophila melanogaster Wdr33 (30% identical), Caenorhabditis elegans pfs-2 (26% identical), zebrafish wdr33 (17% identical).
Diseases named in the same sentence as WDR33 in open-access papers:
WDR33 is named in the same sentence as 11 diseases in open-access papers, as found by Europe PMC text mining. Sharing a sentence is not in itself a finding about the gene and the disease. The quoted sentences say what the papers report.
atrial septal defect (2 papers, 2022 to 2025). Interauricular communication is a congenital malformation characterized by a communication between the atrial chambers of the heart. "According to the MalaCards Human Disease database, WDR33 is associated with the dominantly inherited atrial septal defect, a condition characterized by an atrial septal defect with variable clinical expression." (PMID 40525707, 2025). "In this study, of approximately 100 kb, which is three genes were found near breakpoints in multiple samples, including schizophrenia‐related gene TMEM37 and atrial septum defect associated gene WDR33." (PMID 35384386, 2022).
acute respiratory distress syndrome (1 paper, 2021). Progressive and life-threatening pulmonary distress in the absence of an underlying pulmonary condition, usually following major trauma or surgery. "In particular, the expression of circRNA Slco3a1 was significantly increased and circRNA Wdr33 was markedly reduced in patients with acute respiratory distress syndrome." (PMID 35141166, 2021).
hydrocephaly (1 paper, 2025). "Herein, we have identified a novel phenotype of a complex syndromic form of CP in cattle, including pentalogy of Fallot and hydrocephaly, associated with a dominantly inherited likely pathogenic de novo mutation in the bovine WDR33 gene." (PMID 40525707, 2025).
male infertility (1 paper, 2022). The inability of the male to effect fertilization of an ovum after a specified period of unprotected intercourse. "Particularly, WDR33 had been identified associated with male infertility." (PMID 35384386, 2022).
viral infection (1 paper, 2015). "• In the module of miR-493-3p and miR-214, the sole target mRNA WDR33 of miR-493-3p has been found to result in increased viral infection with two or more siRNAs." (PMID 25707620, 2015).
cancer (3 papers, 2017 to 2025). A tumor composed of atypical neoplastic, often pleomorphic cells that invade other tissues. "Three genes emerged: TARDP (Transcription of RNA activating protein/TAR DNA binding protein); HNRNPK (Heterogeneous Nuclear Ribonucleoprotein K); and WDR33 (WD Repeat Domain 33) as having the lowest CVs across the spectrum of cancers." (PMID 29088295, 2017). "We found that many CPA genes are mutated in cancer, notably PCF11, WDR33, CPSF1, and SYMPK." (PMID 41463412, 2025). "Next, we compared expression of TARDP, HNRNPK, and WDR33 in different cancers." (PMID 29088295, 2017). "The CVs were 0.095, 0.106, and 0.109 for TARDP, HNRNPK, and WDR33, respectively, reflecting variability in gene expression across different categories of cancer that was no greater than the variability observed in different specimens of the same malignancy." (PMID 29088295, 2017).
infection (1 paper, 2015). The state of being infected such as from the introduction of a foreign agent such as serum, vaccine, antigenic substance or organism. "Several infection-induced SUMO targets also are involved in mRNA maturation events, such as 3′ end pre-mRNA processing (CPSF1, CPSF2, FIP1L1, RBBP6, and WDR33), splicing (CLASRP, SFPQ, and ZRANB2), and nuclear RNA quality control (ZC3H18, ZCCHC7, and PAPD5)." (PMID 26549460, 2015).
neurodevelopmental disorder (1 paper, 2025). A behavioral and cognitive disorder with onset during the developmental period that involves impaired or aberrant development of intellectual, motor, or social functions. "In addition, WDR33 has been associated with neurodevelopmental disorders in human patients, and Wdr33 heterozygous mutant mice exhibit abnormal prepulse inhibition implicating a role for WDR33 in neurodevelopment." (PMID 40525707, 2025). "Our results might serve as a starting point for further research into the function and mechanisms of WDR33 in the context of syndromic forms of CP, congenital heart defects, and neurodevelopmental disorders." (PMID 40525707, 2025).
neurological disorders (1 paper, 2025). "Therefore, future studies should be aimed at investigating the role of pathogenic WDR33 variants and their role in the development of syndromes involving craniofacial anomalies, heart defects, and neurological disorders." (PMID 40525707, 2025).
WDR33 also shares sentences with these, for which no sentence is quoted: schizophrenia (1 paper); tumor (1).